HIF1A (hypoxia inducible factor 1 subunit alpha)
Diseases named in the same sentence as HIF1A in open-access papers (continued):
Sharing a sentence is not in itself a finding about the gene and the disease.
atherosclerosis (continued). "Safranin attenuates atherosclerosis by modulating the expression of eNOS and HIF-1α in lipoprotein mice." (PMID 37959658, 2023). "This novel lncRNA AC078850.1/HIF-1α complex was required to advance our understanding of atherosclerosis, as well as to provide potential therapeutic agents against it." (PMID 37371830, 2023). "HIF-1α emerges as a significant contributor to the pathogenesis of conditions including atherosclerosis, PAH, and cardiomyopathy." (PMID 37981648, 2023). "Taken together, the data in this study unveiled that lncRNA AC078850.1 mediated pyroptosis in atherosclerosis via increasing HIF-1α-mediated ITGB2 gene transcription." (PMID 37371830, 2023). "Among the different processes in which miR-199a-5p participate, several targets are implicated in atherosclerosis including ABCA1, ABCG1, Cav-1, HIF1A, CD38, NCOR1, and SIRT1 in human and mouse." (PMID 36407436, 2022). "Because HIF-1α, the active subunit of HIF-1, can inhibit apoptosis by activating a variety of anti-apoptotic genes, it is associated with the development of human atherosclerosis." (PMID 36618414, 2022). "The relationship between HIF-1α and atherosclerosis is well documented and has been reviewed previously." (PMID 35386720, 2022). "In the context of atherosclerosis, one of the best-documented effects of HIF-1α is its action on macrophages." (PMID 35386720, 2022). "In line with a potentially beneficial role, HIF-1α overexpression in mouse lymphocytes was associated with a reduction of IFN-γ expression and a reduced development of atherosclerosis." (PMID 35386720, 2022). "CD163(+) macrophages promote angiogenesis, vascular permeability and inflammation in atherosclerosis via the CD163/HIF1α/VEGF-A pathway." (PMID 36061537, 2022). "Mouse models of atherosclerosis can be used to provide a more direct assessment of the contribution of HIF-1α to atherogenesis." (PMID 35386720, 2022). "Endothelial HIF-1α has been shown to promote atherosclerosis not only through its role in barrier dysfunction, but also by modulating other processes of progression of atherosclerosis such as monocyte recruitment." (PMID 36497143, 2022). "The studies reviewed here shed lights on the complex interplay between hypoxia, HIF-1α, atherosclerosis and cholesterol homeostasis." (PMID 35386720, 2022). "HIF-1α is critical for the development of atherosclerosis through cell-specific responses by acting on endothelial cells, vascular smooth muscle cells and macrophages." (PMID 35741725, 2022). "Because VSMCs functions in atherosclerosis are highly complex, the consequences of HIF-1α-induced VSMCs migration and proliferation are yet to be determined." (PMID 35386720, 2022). "Vascular endothelial growth factor (VEGF)-A is one of the key target genes of HIF-1α, and plays a crucial role in angiogenesis as well as in the development of atherosclerosis." (PMID 36497143, 2022). "Nevertheless, there is undoubtedly a reciprocal regulation between HIF-1α and cholesterol in macrophages in the context of atherosclerosis." (PMID 35386720, 2022). "During inflammatory conditions such as atherosclerosis, hypoxia inducible factor-1 alpha (HIF1α) enhances the release of interleukin-6, tumor necrosis factor alpha, and TSP1, all of which act as profibrotic factors and alter the vascular homeostasis." (PMID 33854480, 2021). "Third, it has been reported that SHNG12 targeting miR‐199a‐5p/HIF‐1α contributed to atherosclerosis formation by mediating the phenotypes of VSMCs." (PMID 34132029, 2021). "On the one hand, HIF-1α activation was shown to promote atherosclerosis initiation and progression as well as hypoxia-induced renal fibrogenesis by stimulating epithelial-to-mesenchymal transition and a2(I) collagen expression through interactions with Smad3." (PMID 34572324, 2021).
atherosclerosis (continued). "The involvement of HIF-1α in diseases of the vascular wall, including atherosclerosis, carotid stenosis, and aneurysms, has recently been proposed." (PMID 31941032, 2020). "In this study, we found that inhibition of HIF1α in cDCs promotes adipose tissue inflammation and accelerates the development of atherosclerosis." (PMID 33257753, 2020). "Increasing studies have found that HIF-1α plays a protective role in atherosclerosis, heart failure and ischemic heart diseases." (PMID 32848792, 2020). "Increasing HIF‐1α expression improves vascular remodelling and ischaemic symptoms in atherosclerosis." (PMID 32865338, 2020). "Another study reported that HIF-1α increases as a consequence of neovascularization in complicated human atherosclerosis among human carotids, as well as in coronary plaques." (PMID 31941032, 2020). "Endothelial dysfunction and proliferation is a vital feature of atherosclerosis formation, and it has proven to be upregulated by HIF1-α." (PMID 32760290, 2020). "Intimal neovascularization is well described in native heart atherosclerosis, thought to be mediated by hypoxia-inducible factor 1-α (HIF-1α) activation in response to hypoxemia of the thickened intimal." (PMID 32351833, 2020). "HIF-1α plays a significant role in the responses of endothelial cells, VSMCs, and macrophages, and thereby promotes the development of atherosclerosis." (PMID 33321972, 2020). "In summary, circRNAs exerted dramatic effects on hypoxia and atherosclerosis; however, the role of circRNAs/HIF‐1α in atherosclerosis needs to be further explored." (PMID 32865338, 2020). "HIF-1α has been identified to play a protective role in the ischemic heart disease, atherosclerosis, and heart failure." (PMID 32848792, 2020). "Endothelial specific heterozygous HIF-1α mouse demonstrated reduced inflammation and atherosclerosis." (PMID 31380363, 2019). "(iii) PRKAA1 and HIF1A have pleiotropic effects unrelated to glycolysis that also influence atherosclerosis." (PMID 30405100, 2018). "Previous studies have shown that disturbed flow enhances endothelial proliferation at atheroprone sites via activation of HIF1A-driven glycolysis and that deletion of endothelial HIF1A reduces atherosclerosis, indicating HIF1A is a driver of atherosclerosis." (PMID 30405100, 2018). "HIF-1α mRNA was found to be markedly up-regulated in both monocytes and lymphocytes of CAD patients than that of controls, and the expression level of HIF-1α was highly correlated with severity of atherosclerosis and higher level of collateral score." (PMID 28595632, 2017). "HIF1α promotes atherosclerosis initiation at these sites by inducing excessive EC proliferation and inflammation via the induction of glycolysis enzymes." (PMID 28882872, 2017). "In summary, mechanical shear stress induces NF-κB– and Cezanne-dependent upregulation of HIF1α at regions of arteries that are prone to atherosclerosis." (PMID 28882872, 2017). "Our studies of arteries from young mice and pigs revealed for the first time that HIF1α is expressed preferentially at low shear stress regions of the arterial tree that are predilection sites for atherosclerosis." (PMID 28882872, 2017). "Numerous studies have analyzed the role of HIF-1α in macrophages and foam cells for processes important in atherosclerosis development." (PMID 27034586, 2016). "Hypoxia-induced HIF-1a/VEGF/Ets-1 cascade was suggested as important for angiogenesis in human atherosclerosis." (PMID 26006236, 2015). "Concurrently, 27 DEGs were hot spots related to atherosclerosis, such as Ace, Apoe, and Hif1a." (PMID 41209003, 2025). "Strikingly, 10 genes exhibited shared dysregulation in both aging and atherosclerosis, including Vcam1, Apoe, Gdf15, Timp1, Cxcl12, Hspd1, Serpine1, App, Eln, and Hif1a, suggesting their potentially critical roles in the atherosclerosis driven by aging in HGPS mice." (PMID 41209003, 2025).
atherosclerosis (continued). "Moreover, macrophage was participated in HIF-1α signaling pathway to enhance the effects of atherosclerosis." (PMID 39891057, 2025). "Inhibiting HIF-1α in adipocyte improves atherosclerosis through impairing ceramide generation." (PMID 40478326, 2025). "The expression of HIF-1α was up-regulation with atherosclerosis." (PMID 39891057, 2025). "Whether hypoxia- and oxidized LDL (oxLDL)-induced HIF-1α is harmful or beneficial in atherosclerosis depends on the specificity of cell type and the context in which it occurs." (PMID 40376262, 2024). "Together, these studies suggest the dual role of HIF-1α in atherosclerosis; whether HIF-1α is detrimental and protective is likely influenced by cell type specificity and context dependency." (PMID 40376262, 2024). "HIF-1α, as the target of roxadustat, may contribute to the development of atherosclerosis in which inflammation and dyslipidemia are of the most importance." (PMID 36724056, 2023). "Furthermore, previous research mainly studied HIF-1α’s link to atherosclerosis, while recent studies are exploring HIF-2α’s role." (PMID 37981648, 2023). "Also, miRNAs have an essential role during inflammatory processes and their relationship with genes such as HIF-1α can be considered to study the process of atherosclerosis." (PMID 37005512, 2023). "The transcription factor, hypoxia-inducible factor-1 (HIF-1α), affects multiple biological abilities of macrophages and promotes the development of atherosclerosis, but its potential mechanism is still unknown." (PMID 37371830, 2023). "Normoxic endothelial HIF-1α stabilization plays an important role in the inflammatory response of ECs to MFs, which could play a crucial role in the progression of atherosclerosis." (PMID 36497143, 2022). "In atherosclerosis, HIF1α−/− downregulated 4 canonical SGs and 7 exosomes SGs." (PMID 35320939, 2022). "However, besides KLF2/4, hemodynamic forces activate several signaling pathways to regulate endothelial phenotypes associated with atherosclerosis, via other transcription factors, such as YAP/TAZ, NRF2, HIF-1a, NF-κB and AP-1." (PMID 35883633, 2022). "Finally, we discuss the consequences of theses “dangerous liaisons” in the pathogenesis of atherosclerosis and the potential interest of pharmacological targeting the HIF-1α-cholesterol axis." (PMID 35386720, 2022). "The HIF-1α-IL-1β axis is of peculiar interest in the context of atherosclerosis." (PMID 35386720, 2022). "In conclusion, the impact of HIF-1α on cholesterol homeostasis within macrophages and the feedback activation of the inflammatory response by oxysterols via HIF-1α could play a deleterious role in atherosclerosis." (PMID 35386720, 2022). "While several levels of evidence support the hypothesis that HIF-1α could be pro-atherogenic within atheroma plaques, experimental models of atherosclerosis in mice suggest a complex role that depends on the cell type or the organ in which HIF-1α is present." (PMID 35386720, 2022). "Since G-CSF can cause normoxic HIF-1α stabilization, a feedback loop between G-CSF and HIF-1α might also be formed, which could further accelerate the progression of atherosclerosis." (PMID 36497143, 2022). "HIF-1α exerts both detrimental and beneficial actions in atherosclerosis." (PMID 35386720, 2022). "Interestingly, this pathway is relevant in the context of atherosclerosis since HIF-1α and LXRα co-localize in the nuclei of macrophages within the plaque." (PMID 35386720, 2022). "Regarding atherosclerosis, the impact of HIF-1α appears to depend on whether we consider the cells present within the plaque or the effects of systemic modulation of HIF-1α." (PMID 35386720, 2022). "Finally, in the same model of atherosclerosis-sensitive mice, specific Hif1a deletion in smooth muscle cells reduced vascular inflammation and atherosclerosis." (PMID 35386720, 2022).
atherosclerosis (continued). "While there is evidence that HIF-1α could be pro-atherogenic within the atheromatous plaque, experimental models of atherosclerosis suggest a more complex role that depends on the cell type expressing HIF-1α." (PMID 35386720, 2022). "HIF-1α is stabilized in macrophages and smooth muscle cells near the necrotic core of atherosclerotic vascular lesions in humans and in animal models, and HIF-1 has been implicated in atherosclerosis progression." (PMID 35432002, 2022). "Karshovska and his colleagues found that HIF-1α could increase atherosclerosis by necrotic core formation." (PMID 33226577, 2021). "Importantly, agent that inhibits HIF-1α-induced inflammation and apoptosis in macrophages can be used for the treatment of atherosclerosis." (PMID 34465337, 2021). "Studies have indicated that rescue of HIF‐1α expression could restore hind limb ischaemia in rats with diabetes and atherosclerosis." (PMID 32865338, 2020). "Notably, activated macrophages in atherosclerosis have been observed to stabilize HIF-1α under normoxic conditions." (PMID 31941032, 2020). "In addition, ox‐LDL induced a variety of transcription factors, including HIF‐1α, during the atherosclerosis development, which established the significance of ox‐LDL/circ_0000345/HIF‐1α signalling in the occurrence and development of atherosclerosis." (PMID 32865338, 2020). "The exact mechanism that mediates ECs to become senescent in the vascular wall is still not fully understood; however, much evidence has revealed a crucial role for hypoxia-inducible factor-1α (HIF-1α) in the development of the senescent phenotype and the progression of atherosclerosis." (PMID 31941032, 2020). "On the contrary, it has been demonstrated that HIF-1α plays a role in the progression of atherosclerosis suggesting that the repression of its activity could lead to beneficial outcome for patients." (PMID 31289332, 2019). "Thus, mechanical activation of HIF1α is a novel mechanism for the focal induction of atherosclerosis." (PMID 28882872, 2017). "In human atherosclerosis, HIF-1α protein co-localizes with macrophages." (PMID 20727156, 2010). "However, deletion of HIF-1α in CD11c+ antigen-presenting cells accelerated atherosclerotic plaque formation and increased lesional T-cell infiltrates, highlighting its protective role against atherosclerosis." (PMID 40376262, 2024). "However, it has been suggested that hypoxia-induced HIF-1α accumulation upregulates the expression of its target genes and affects the lipid metabolism of hypoxic macrophages in atherosclerosis, thereby providing evidence of a possible atherogenic role for hypoxia." (PMID 35205167, 2022). "Therefore, increasing HIF‐1α expression may be capable of promoting vascular remodelling and improving ischaemic symptoms in atherosclerosis." (PMID 32865338, 2020). "In this model, local and systemic T-cell activation, as well as TH1 polarization, further suggest the involvement of HIF-1α in DCs in restraining T-cell activation and TH1 polarization during atherosclerosis development." (PMID 38397127, 2024). "Hemoglobin-haptoglobin receptor CD163 positive macrophages were associated with plaque progression, microvascularity, and a high level of HIF1α and VEGF-A expression in atherosclerosis." (PMID 39364414, 2024). "In atherosclerosis, anaerobic metabolism and pro-inflammatory activation of macrophages is dependent on HIF-1α, and a change in HIF-1α protein levels directly affects the expressional level of PDK." (PMID 38193078, 2023). "In parallel, the expression of HIF-1α target genes (e.g., GLUT1, GLUT3 and HK1) is significantly increased during the progression from early to advanced atherosclerosis development, reflecting enhanced reliance on glycolysis in macrophages." (PMID 37863894, 2023).
atherosclerosis (continued). "Activation of LPAR1 and LPAR3 can promote the expression of hypoxia-inducible factor 1 subunit alpha (HIF-1α), then upregulate C-X-C motif chemokine ligand 1 (CXCL1) in cells, thereby accelerating atherosclerosis." (PMID 37342437, 2023). "Hypoxia plays a key mechanistical role during atherosclerosis and upregulates ABCA1 in macrophages through HIF1α transcription factor." (PMID 36407436, 2022). "Recent findings revealed that atheroma plaque homogenates increased human macrophages’ HIF-1α by forming liver-X-receptor (LXR)-HIF-1α-complexes on HIF-1α- and IL-1β-promoter-regions promoting inflammation in atherosclerosis." (PMID 33808042, 2021). "Firstly, we demonstrated that RSV might inhibit ferroptosis to exert anti‐atherosclerosis effect; In addition, RSV regulates ferroptosis mainly through six biomarkers, including IL1B, RELA, HIF1A, SRC, PTEN, and MAPK1, in AS treatment." (PMID 40697701, 2025). "The effect of lncRNA AC078850.1 in atherosclerosis is unknown; this study aims to explore the regulatory mechanism of the lncRNA AC078850.1/HIF-1α complex in atherosclerosis." (PMID 37371830, 2023). "HIF-1α activation in inflammatory macrophages induces ox-LDL uptake, reactive oxygen species (ROS) accumulation and necroptosis, all of which contribute to necrotic core formation in atherosclerosis." (PMID 37371830, 2023). "In this study, we aimed to explore atherosclerosis-related lncRNA AC078850.1 and its transcription factor (HIF-1α) based on bioinformatic analysis, as well as the regulatory mechanism of the lncRNA AC078850.1/HIF-1α complex in atherosclerosis." (PMID 37371830, 2023). "HIF-1α and HIF-2α play an antagonistic effect in the long-term activation process, which may contribute to the progression of chronic heart failure, atherosclerosis, hypertension, vascular disease, and chronic kidney disease cardiac failure." (PMID 36420092, 2022). "Importantly, HIF-1α is highly expressed in smooth muscle cells and cardiomyocytes, which underscore the potential role of a possible profilin-SIRT3-HIF-1α axis in atherosclerosis." (PMID 33499277, 2021). "Endothelial HIF1A and PRKAA1 play complex roles in atherosclerosis." (PMID 30405100, 2018). "Investigation also showed that HIF-1α, a downstream transcription factor of ox-LDL, could affect lesional macrophage inflammatory profile and promote development of atherosclerosis." (PMID 29126450, 2017). "Despite the current study sufficiently presenting the function of lncRNA AC078850.1/HIF-1α regulatory complex in atherosclerosis in vitro, there was still a lack of attention to the functional validation in vivo due to the low homology of lncRNA AC078850.1 in mice." (PMID 37371830, 2023). "Moreover, unstable plaque highlights the relationship between atherosclerosis and HIF-1α in ECs and macrophages, independent of their origin (SASP or SIPS)." (PMID 31941032, 2020). "Thus, we hypothesized that increased VAT inflammation in Hif1α−/− mice might have a negative impact on the development of atherosclerosis." (PMID 33257753, 2020).
atherosclerosis (continued). "Moreover, as a ROS-related protein, ITGB2 could interact with multiple genes (e.g., HIF-1α) to promote ROS production, NLRP3 inflammasome activation, pyroptosis, and foam cell formation in macrophages, suggesting its potential role in the progression of atherosclerosis." (PMID 41348730, 2025). "Although several factors related to hypoxia such as HIF1A and downstream targets of the HIF pathway, such as PDK-1 and VEGF, have been studied in detail in atherosclerosis, HIF3A expression has not previously been reported." (PMID 40034249, 2025).